IL10 (interleukin 10)
Diseases named in the same sentence as IL10 in open-access papers (continued):
Sharing a sentence is not in itself a finding about the gene and the disease.
tumor (continued). "Importantly, IL-10 blockade increased the survival of tumor-bearing mice by 30%." (PMID 38912586, 2024). "Furthermore, metformin decreased IL-10+ and FoxP3+ Tregs, along with Gr-1+ myeloid-derived suppressor cells (MDSCs) in spleens, and in tumor tissue, it decreased IL-10+ and FoxP3+ Tregs, Gr-1+, NF-κB+, and iNOS+ MDSCs, and iNOS+ dendritic cells (DCs), while increasing the DCs quantity." (PMID 38892058, 2024). "However, if tumor cells survive and rearrange, then IL-10 in the tumor microenvironment may act as a powerful tumor promoter." (PMID 38349555, 2024). "However, the vvDD-IL-9 treatment significantly elevated the levels of IL-10 mRNA in the tumor on day 9, suggesting that secondary IL-10 upregulation might enhance the persistence of vvDD-IL-9 in the tumor." (PMID 38473379, 2024). "Furthermore, tumor-produced factors (e.g., IL-4, IL-10, TGFß1, and PGE2) contribute significantly to the functional polarization of monocytes/macrophages into immunosuppressive cells, highlighting the intricate interplay between tumor cells and the immune system." (PMID 39410029, 2024). "Probiotics can reduce intestinal and skin inflammation by increasing serum IL-10 levels and inducing expression by regulatory T cells, while decreasing IL-17 levels, can act as antioxidants, and can induce the expression of tumor-suppressor genes to fight tumor cells." (PMID 38562964, 2024). "In addition, EPSs can play an anti-inflammatory and anti-tumor role by enhancing the activity of T cells, B cells, NK cells and macrophages, promoting the expression of cytokines such as TNF-α and IL-10, and inducing apoptosis of tumor cells and scavenging of free radicals." (PMID 38450163, 2024). "Thus, it is plausible that the heightened levels of IL10 detected in CAC mice originate from the recruited MDSCs following their interaction with the bacteria, consequently shifting the function of IL10 an inflammation-resolving cytokine to a tumor-promoting one." (PMID 38506672, 2024). "Additionally, Tregs from KD-fed animals produced less IL-10 when stimulated with tumor cells." (PMID 38594256, 2024). "However, the role of IL-10 in regulating anti-tumor immunity remains a subject of debate." (PMID 38291041, 2024). "Mechanistically, MDSC-mediated inhibition of anti-tumour immunity occurs through a myriad of pathways including expression of arginase 1 (Arg1), inducible nitric oxide synthase (iNOS) and reactive oxygen species (ROS), and secretion of immunosuppressive cytokines such as interleukin 10 (IL-10)." (PMID 38464388, 2024). "Although low values of intracellular IL-10 were found in CD4+ T cells, the high values of that cytokine observed in the culture supernatant associated with high IL-4 suggest an anti-inflammatory profile (Th2) promotion by HPV oncogenes present in the transfected A549 tumor cells." (PMID 39599846, 2024). "Thus, the number of immunosuppressor cells in the TME is significantly reduced, and their function is inhibited, resulting in downregulated expression levels of TGFβ and IL-10 in tumor tissues, and therefore the immunosuppressive TME is systematically relieved." (PMID 38807760, 2024). "However, IL-10 represents a pleiotropic cytokine and whether it is a tumor-promoting or -inhibiting agent is context dependent and still requires further investigation." (PMID 38500875, 2024). "Moreover, unfavorable outcomes were strongly associated with the expression of CD59 and M2 tumor-associated macrophage infiltration in the TME via the IL10/pSTAT3 pathway in CESC and GBM but not in KIRC." (PMID 39518137, 2024). "Finally, T cell inhibition may be directly triggered by tumor cell-secreted cytokines, including IL-4, IL-10 and TGF-β; it has been reported that ABCB5+ melanoma cells express and release in the TME high levels of TGF-β-related factors." (PMID 39199632, 2024).
tumor (continued). "Furthermore, NF-κB and STAT3 interact and cooperate in regulating the interaction of malignant cells and the tumor microenvironment, especially immune cells such as TAMs that release cell-stimulating growth factors and cytokines, including IL-6, IL-10, and TNF-α." (PMID 39061137, 2024). "Likewise, IL-10 secreted by DCs in the TME could increase the number of tumor-infiltrating MDSCs, conferring adaptive resistance to PD-1 antibody treatment." (PMID 38520006, 2024). "Therefore, decreased IL10RB expression may enhance immune surveillance by diminishing IL-10-mediated immunosuppression in the tumor microenvironment." (PMID 39769247, 2024). "The tumor microenvironment might be associated with increased cytokines from regulatory T cells that secrete immunosuppressive cytokine–chemokines, such as TGF-beta and IL10, which suppress the activation, proliferation, and functions of CD8+ T cells." (PMID 38540240, 2024). "We evaluated the cytokine profiles of cells isolated from CRC tumor tissue and observed a time-dependent increase in the expression of the pro-inflammatory cytokines TNFα and IFNγ for all different treatment groups, whereas downregulation of anti-inflammatory cytokine IL10." (PMID 39164686, 2024). "In addition, local production of IL-10 lead to the exclusion of APC from the tumor mass." (PMID 39136031, 2024). "Furthermore, it has been proposed that high levels of IL-22, IL-10, and CCL20 may determine, as a cascade event, the overexpression of IL-22–STAT3–CCL20–CCR6 thought to be associated with a tumor’s ability to spread to the lymph nodes and internal organs." (PMID 38607023, 2024). "Furthermore, the adoptive transfer of B-1a cells from wild-type mice, rather than IL-10- deficient mice, resulted in a significant increase in tumor growth." (PMID 38629061, 2024). "In addition, we found that among others IL-6 and IL-10 levels correlated with IL-8 levels, which may reflect the inflammatory microenvironment of the tumor, the latter also known for its inhibitory effect on the immunosurveillance." (PMID 39503874, 2024). "Notably, in certain TMEs, IFN-I exhibit opposing effects to induce the expression of cell death ligand 1 (PD-L1), enzyme IDO (indoleamine 2,3-dioxygenase), interleukin-10 (IL-10), regulatory T cells (Tregs) and other anti-inflammatory mediators, to evade the tumor-induced immune suppressive TME." (PMID 38672681, 2024). "Notably, all M2 macrophages produce IL-10, an immunosuppressive cytokine critical for tumor growth." (PMID 38185636, 2024). "In addition, MerTK signaling promotes the secretion of anti-inflammatory cytokines, such as transforming growth factor-β (TGFβ), hepatocyte growth factor (HGF), and IL-10, resulting in immunosuppressive, pro-tumor, M2-polarized macrophages in the tumor microenvironment (TME)." (PMID 38443968, 2024). "However, Tregs are important suppressors in the tumor environment, while IFNγ prevents the neogeneration of Tregs through reactive oxygen species (ROS)-mediated apoptosis, and counteracts IL-10 and Transforming growth factor-β (TGF-β) signaling-mediated inhibition." (PMID 38827732, 2024). "Moreover, other cytokines such as IL‐6, IL‐1β, VEGF, and IL‐10 have been correlated with poor prognosis in cancer patients due to their role in regulating myeloid cell (e.g., MDSCs) differentiation and recruitment to the tumor." (PMID 37681284, 2024). "Moreover, an even sharper decline in IL-10 levels is demonstrated as tumor volume begins to grow." (PMID 39451257, 2024). "However, after EC has developed, elevated IL-10 levels might contribute to more complex interactions within the tumor microenvironment." (PMID 39496002, 2024). "These cells may induce immunotolerance through the expression of immune-checkpoint proteins, such as PD-1 and CTLA-4, on the surfaces of cells, interfering with the immune response at the tumor site, in addition to the secretion of immunomodulators, such as interleukin 10, interleukin 35, and TGF-β." (PMID 37111629, 2023).
tumor (continued). "However, IFN-γ stimulated type 1 immunity may counteract the functions of tumor immunosuppressive type 2 cytokines (TGFβ and IL10)." (PMID 37190251, 2023). "Tumor-growth factor (TGF) and platelet-derived growth factor (PDGF) induce the transformation of tumor fibroblasts (FHNR) in cancer-associated fibroblasts (CAFs), which play a key role in tumor progression, producing pro-tumoral cytokines (e.g., IL-6, IL-8, TNF, IL-10)." (PMID 37842234, 2023). "Interestingly, IL6 is known to promote tumor growth by upregulating antiapoptotic and angiogenic proteins in tumor cells, and elevated IL10 may inhibit tumor growth by suppressing IL6 production." (PMID 37238004, 2023). "Particularly, the combination of IL-10-blocking antibody administration together with other immunostimulatory approaches, such as mifamurtide treatment, could be a promising strategy for aggressive and resistant OS tumor treatment." (PMID 37835437, 2023). "However, the expression levels of typical anti-inflammatory cytokines, Il4, Il10, and Il13, which are predominantly produced by tumor-associated macrophages (TAM) in the tumor microenvironment (TME), were similar between the control and creatine-supplemented groups." (PMID 37662917, 2023). "Moreover, although increased frequency, proliferation and IL-10 secretion of CD24hiIgDlo/−CD38lo Bregs in dLNs were detected in tumor-bearing mice treated with FGK compared to the controls treated with Rat IgG, the levels were significantly lower in mice treated with FGK plus GSK." (PMID 37291146, 2023). "The cells in seqC1_FoxP3int had a relatively low expression of FoxP3, CD25, CTLA-4, HLA-DR, PD-1 and IL-10, and a high expression of IL-17, indicating that these may be pro-inflammatory Tregs induced in an inflammatory microenvironment in these tumor and lymph node tissues." (PMID 37232845, 2023). "Furthermore, indirect suppression via macrophages secreting Interleukin-10 (IL-10) to reduce dendritic cell capacity to secrete IL-12 and induce the anti-tumor immune response of TH1/CTL or recruitment of IL-10 expression via Regulatory T cells (TReg) via chemokine CCL22." (PMID 37039909, 2023). "However, IL-10 is also involved in tumor immune escape, as it is an immunosuppressive cytokine." (PMID 38011277, 2023). "Moreover, ELISA results showed that the concentration of iNOS (which often represents anti-tumor, pro-inflammatory M1-like macrophages) increased and IL10 (which often represents pro-tumor, anti-inflammatory M2-like macrophages) decreased in the supernatant of TAMs." (PMID 36639372, 2023). "However, it has been shown that CD4+ T cells can also secrete some cytokines, such as IL-10, which can inhibit tumor angiogenesis through a variety of pathways, such as inhibiting endothelial cell proliferation and migration, and reducing the secretion of vascular endothelial growth factor." (PMID 37342362, 2023). "Moreover, PepO significantly switched TAM to the tumoricidal M1 macrophage as reflected by a reduction in the expression of M2 markers Arg-1, CD206, Fizz-1, Ym1 and IL-10 while increasing the expression of M1 markers iNOS, IL-12a and IL-1β and promoted apoptosis of the tumor cells." (PMID 37925462, 2023). "However, in malignant gliomas, M2-polarization of microglia leads to an immunosuppressive and tumor-supportive phenotype triggered by a series of tumor cytokines, such as transforming growth factor-β, interleukin-10, and prostaglandin E2 and other growth factors." (PMID 35654889, 2023). "The ratio of IL10 to IFNγ produced by the Tr1-like cytotoxic CD4 T cells could be a key determinant in whether Tr1-like cytotoxic CD4 T cells have a net pro-tumor or anti-tumor impact." (PMID 37654482, 2023). "Furthermore, engagement with agonistic anti-CD40 antibody may stimulate IL-10+ Bregs, leading to an increase in number and function in tumor-bearing mice by a mechanism largely dependent on PPARδ." (PMID 37291146, 2023).
tumor (continued). "Furthermore, migration of IL-10-secreting regulatory CD4+ T cells (Tregs) into the tumor environment can be induced by EBNA1-mediated upregulation of CCL20 on tumor cells, leading to the induction of immune tolerance through the suppression of cytotoxic CD8+ T cells." (PMID 37033971, 2023). "Moreover, tumor cells and tumor-associated macrophages (TAMs- M2 phenotype) may release products (TGF-β, IL-10, VEGF, prostaglandin E2, etc.), which are able to block the proliferation and functions of lymphocytes and macrophages." (PMID 37189689, 2023). "Moreover, IL‐10 can inhibit IFN‐γ secretion by tumor‐infiltrating CD8+ T cells." (PMID 36043445, 2023). "Therefore, in the current study, we investigated the amount of F. nucleatum and its relationship with the expression of inflammatory genes (TLR-2, TLR-4, TNF-α, IL-6, IL-10, IL-12β, and IL-17) and miRNAs (miR-21, and miR-31) in tumor and adjacent normal tissue of Iranian CRC patients." (PMID 38075864, 2023). "Interestingly, except for IL-10, the other four could not only predicted an excellent prognosis, but also had relatively low expression in tumor tissues." (PMID 37553698, 2023). "Hence, we put forward a hypothesis that one of the factors which may have an adverse influence on the functions of DCs administered peritumorally as cellular vaccines, is IL-10 which is abundantly present in tumor tissue." (PMID 37033926, 2023). "However, a recent study suggests that IL-10 contributes to gemcitabine resistance in ENKTL cell lines by regulation of drug resistance genes, suggesting that inhibition of IL-10 in select patients may be utilized to increase tumor sensitivity to chemotherapy." (PMID 36900160, 2023). "In addition to interacting with local immune cells in an inflammatory TME, secreted TGF-β may stimulate tumor cells and MDSCs to release IL-10." (PMID 38033495, 2023). "However, factors involved in increased IL-10 expression by the tumor are not well understood." (PMID 36830840, 2023). "Tumor-mediated immunosuppression could be caused by the release of immunosuppressive cytokines, such as TGF-β and IL-10; the expression of immune checkpoint inhibitors, such as programmed cell death protein 1 (PD-1); or by the presence of immunosuppressive cells, such as CD4+ Treg cells." (PMID 37238744, 2023). "However, based on the characteristics of immunosuppression, M2 macrophages play the opposite role, clearing debris, promoting angiogenesis, tissue remodeling, repairing anti-inflammatory and promoting tumor effects, which are characterized by high IL-10 and low IL-12 phenotypes 19-21." (PMID 37151385, 2023). "Joint decrease in IL-2 and IL-4 could be inducing a decrease in certain Tregs function after NAC, which would explain the stromal and tumor decrease in FoxP3 reported here, as well as the significant association between post-NAC expression of IL-10 and IL-17 and failure to obtain pCR." (PMID 37104271, 2023). "Results showed that conditioned medium from FAP-over-expressed LX2 cells could decrease the expression of M1 markers like iNOS, TNF-α and IL-1β but increase the expression of M2 markers like IL-10 in macrophages as compared to NC group, transforming the macrophages into M2 pro-tumor phenotype." (PMID 37325617, 2023). "They inhibit the anti-tumor immune responses through multiple mechanisms including the depletion of key amino acids (e.g., tryptophan, L-arginine), production of inhibitory factors (IL-10, TGF-β) that suppress T cell effector functions and recruitment of regulatory T cells to the TME." (PMID 37046671, 2023). "In addition, SEMA4A could regulate the secretion of IL-10 in stromal cells and coordinates with IL-10 to promote tumor cell invasion via inducing Epithelial-mesenchymal transition." (PMID 37779872, 2023). "Additionally, whilst PD-L1 expression may protect macrophages from cell death, OSCC tumour cells induce TAM PD-L1 expression via IL-10 and induce T-cell apoptosis, further reinforcing an unfavourable prognosis." (PMID 37397243, 2023).
tumor (continued). "Nonetheless, whether IL-10 promotes or inhibits tumor growth has to be determined." (PMID 38096329, 2023). "In addition, treatment with clodronate in advanced tumor stages has been shown to effectively reduce M2 phenotypic markers, including IL-10, TGF-β, CCL17, and MCP-1.104Fusobacterium nucleatum is a type of bacteria that does not require oxygen to survive and has a rod-like shape." (PMID 37943609, 2023). "Moreover, TNF-α was positively correlated with tumour weight in the experimental mice and considered a potent cancer cachexia factor that could be inhibited by the anti-inflammatory cytokine IL-10." (PMID 38041080, 2023). "Indeed, analysis of tumor infiltrating macrophages from in situ tumor tissue following LL-37 treatment showed macrophages characterized by high IL-10 and low IL-12p35 expression levels, thereby implicating FPR2 signaling in regulating the phenotype of tumor-associated macrophages." (PMID 36817589, 2023). "In addition, DCs contribute to tumor progression by producing IL-10 and tolerogenic signals." (PMID 37735675, 2023). "TAMs at the tumor site, stimulated by different cytokines, differentiate into M1-type macrophages (pro-inflammatory phenotype) with anti-tumor effects or M2-type macrophages (anti-inflammatory phenotype) that inhibit anti-tumor effects and release IL-4, IL-10, and IL-13." (PMID 37055849, 2023). "Thus, we speculate that CSF cfDNA and IL-10 are generated in different ways, the former from tumor cells and the latter from both tumor cells and the tumor microenvironment." (PMID 36644235, 2023). "Thus, it is assumed that persistent exposure to tumor-induced IL-10 may exhaust NK cells as reported for IL-15 induced exhaustion." (PMID 36830840, 2023). "However the subunit alpha can also bind to the Epstein-barr virus-induced gene 3 (Ebi3) protein to form the IL-35, a cytokine known to promote tumor growth and metastasis by converting resting B and T cells into IL-10- and IL-35-producing regulatory B (Breg) and T (Treg) cells." (PMID 37435060, 2023). "Furthermore, treatment of tumor-bearing mice with PPARδ inhibitor could efficiently diminish the number and function of IL-10+ Bregs, and act synergistically with anti-CD40 or anti-PD1 antibody to improve antitumor immune responses." (PMID 37291146, 2023). "Notably, the transfer of CART19-28z SNX9 KO was accompanied with increased serum levels of anti-tumor effector molecules IFNγ, Perforin, and Granulysin, while we detected a decrease in IL10 and IL6 (human CCL5 could not be detected in the serum)." (PMID 36732507, 2023). "Consequently, conditional deletion of Il10 specifically within T cells, and blockade of IL-10 receptor (IL-10R) signaling during Treg cell depleting immunotherapy reversed treatment failure and resulted in enhanced tumor clearance." (PMID 38100544, 2023). "In addition, tumor-infiltrating mast cells could contribute to the evasion of anti-tumor immunity through the release of IL-10 and TGF-β in ccRCC." (PMID 36837389, 2023). "The use of this 80 kDa polymer was associated with the enhanced production of anti-tumour inflammatory/Th1 cytokines, as well as a higher expression of immune-stimulating cytokines, such as IFN-γ and reduced excretion of immunosuppressive cytokines, such as IL-10 in HNSCCs cell lines." (PMID 36980527, 2023). "In addition, exposed macrophages may produce IL-10 cytokine as an immunosuppressive function and matrix metallopeptidases (MMPs) to maintain tumor progression." (PMID 35625975, 2022). "Although we did not observe tumor formation on tumorigenicity risk assays after IL10-MSC transplantation in SCID mice, we still need to determine whether exogenous gene introduction activated tumor-associated signaling pathways." (PMID 35300585, 2022).